PI3 (peptidase inhibitor 3)
Diseases named in the same sentence as PI3 in open-access papers (continued):
Sharing a sentence is not in itself a finding about the gene and the disease.
chondrosarcoma (2 papers, 2014 to 2018). A malignant cartilaginous matrix-producing mesenchymal neoplasm arising from the bone and soft tissue. "Our study revealed that the GABAB receptor antagonist had anti-tumor effects in OUMS-27 cells, a high-grade chondrosarcoma cell line, through cell cycle arrest at G1/S phase and induced apoptosis via dual inhibition of the PI3/Akt/mTOR and MAPK signaling pathways." (PMID 29514603, 2018). "Though PI3/Akt signalling pathway can be activated by TNF-α in human smooth muscle cells or IL-1β in rat brain astrocytes, our results are consistent with BDNF-induced migration in human chondrosarcoma through a transducing signal involving TrkB." (PMID 25418464, 2014).
colitis (2 papers, 2021 to 2022). Inflammation of the colon. "Recombinant or overexpressed PI3 in animal models has demonstrated a protective role in a wide range of experimental tissue injuries including, for example, viral myocarditis, myocardial infarction, heart transplantation, colitis, pulmonary inflammation and vein graft degeneration." (PMID 35008981, 2022).
dementia (2 papers, 2023 to 2024). Loss of intellectual abilities interfering with an individual's social and occupational functions. "PI3 showed the strongest association with cognitive impairment and dementia, possibly due to its role in the regulation of inflammation." (PMID 38337499, 2024).
esophageal cancer (2 papers, 2018 to 2024). A primary or metastatic malignant neoplasm involving the esophagus. "Recently, increasing number of publications focusing on contributive roles of the CXC chemokine receptor 4 (CXCR4) on growth and cell cycle of OSCC and esophageal carcinoma using PI3/Akt were reported." (PMID 29381751, 2018). "According to xiantao database, PPL, PI3, LCE3E, and TGM1 were more expressed in esophageal cancer than normal tissues (p < .05)." (PMID 38241178, 2024).
head and neck cancer (2 papers, 2014 to 2023). A primary or metastatic malignant neoplasm affecting the head and neck. "Over-expression has been shown to increase tumor growth and suppress PI3/AKT-dependent apoptosis in head and neck cancer." (PMID 25093596, 2014). "Importantly, ADAMTS12 was shown to promote cell invasion and the migration of head and neck cancer cells via the activation of the PI3-AKT pathway." (PMID 37835389, 2023).
influenza (2 papers, 2015 to 2018). An acute viral infection of the respiratory tract, occurring in isolated cases, in epidemics, or in pandemics; it is caused by serologically different strains of viruses (influenzaviruses) designated A, B, and C, has a 3-day incubation period, and usually lasts for 3 to 10 days. "The transcript levels of IFI27 and PI3 in these subjects were more similar to the non-influenza infection cases." (PMID 26070066, 2015). "In addition to IFI27 and PI3 that have the largest expression difference between influenza and HRV, CDKN1A and CDKN1C, which are essential genes involved in cell cycle control, appeared to be differentially expressed specifically in influenza virus infection." (PMID 26070066, 2015). "In influenza, IFI27 is upregulated and PI3 downregulated relative to human rhinovirus." (PMID 30271886, 2018).
lung diseases (2 papers, 2006 to 2020). "Peptidase inhibitor 3 (PI3) inhibits neutrophil elastase and proteinase-3, and has a potential role in skin and lung diseases as well as in cancer." (PMID 16719916, 2006).
oral cancer (2 papers, 2020 to 2023). "Nicotine upregulated SNCG expression by activating the α7-nAChRs/PI3/AKT signaling that are participated in nicotine-induced oral cancer malignancy." (PMID 32669976, 2020).
osteosarcoma (2 papers, 2014 to 2020). A usually aggressive malignant bone-forming mesenchymal neoplasm, predominantly affecting adolescents and young adults. "Compared to normal bone tissue, metabotropic glutamate receptor (mGluR) has been reported to be highly expressed in osteosarcoma tissues as well as related to poor prognosis, and it is well known that active mGluR signaling is linked to the PI3/AKT/mTOR pathway." (PMID 33210231, 2020).
pancreatic adenocarcinoma (2 papers, 2016 to 2017).
thyroid cancer (2 papers, 2021 to 2024). "We have described somehow similar effects in a thyroid carcinoma cell line, where inhibition of MEK/ERK1/2 signalling inhibits proliferation, but promotes migration, an effect that can be prevented by a parallel inhibition of the PI3/Akt pathway." (PMID 34769389, 2021).
type 2 diabetes (2 papers, 2018 to 2024). "Sub-cellular network analysis demonstrated the metabolites shared biological significance underlying canonical signaling pathways such as insulin, AMPK, PI3-Akt, and type 2 diabetes signaling pathway, but not ADMA." (PMID 29391561, 2018).
acute myeloid leukaemia (1 paper, 2023). "Recent investigations have also showed that ASH induces autophagy via the PI3/AKT pathway, which controls its apoptosis induction in acute myeloid leukaemia (AML) cells." (PMID 36829578, 2023).
amoebiasis (1 paper, 2022).
arteriosclerosis (1 paper, 2025). A vascular disorder characterized by thickening and hardening of the walls of the arteries. "Studies have demonstrated that inflammatory mediators such as fractalkine/CX3CL1, CCL8, M-CSF, HGF, E-selectin, PI3/elafin, CCL17, and IL-16 are significantly elevated in patients with AD, contributing to the progression of arteriosclerosis." (PMID 40757030, 2025).
bacterial sepsis (1 paper, 2025). "This study aimed to evaluate the efficacy of two transcripts, IFI44L and PI3, in the early differentiation between SFTS virus (SFTSV) infection and bacterial sepsis, as well as in the prompt identification of severe cases during epidemic seasons." (PMID 39688402, 2025).
bronchial carcinoma (1 paper, 2006). "Higher levels of PI3 were also observed in bronchial secretions from patients with chronic obstructive pulmonary disease and bronchial carcinoma, and the expression of PI3 was decreased in breast and in epidermal tumors." (PMID 16719916, 2006). "Initially, PI3 was identified in human epidermis of psoriatic patients, and later in bronchial secretions from patients with bronchial carcinoma and chronic obstructive pulmonary disease, as well as in epidermal and breast tumors." (PMID 16719916, 2006).
celiac disease (1 paper, 2024). An autoimmune genetic disorder with an unknown pattern of inheritance that primarily affects the digestive tract. "Specific coding regions of the PI3 gene-splice variants predispose the Elafin protein, both at the transcriptional and post-translational levels, to modify its expression and function, resulting in reduced differential functional protein levels in patients with active celiac disease." (PMID 38255930, 2024). "We characterized the expression and function of the CD200–CD200R axis and PI3 in celiac disease." (PMID 38255930, 2024).
cholesteatoma (1 paper, 2012). A pathologic process characterized by the proliferation of keratinizing squamous epithelium resulting in the accumulation of keratin and cells in the middle ear and/or mastoid. "Real-time PCR of PI3, SPRR1B, LCN2 (lipocalin 2), MMP1, MMP9, MMP10, MMP12, SPP1, GJB2, Bcl-xl (BCL2L1), cIAP2 (BIRC3), S100A7A (koebnerisin), S100A9, SERPINB3, CEACAM6, KRT6B and SERPINB4 revealed that the expression levels of these proteins were higher in cholesteatoma than in external canal skin." (PMID 23285167, 2012).
cognitive decline (1 paper, 2019). "Our data reveal that α7-nAChR attenuates cognitive decline and neuroinflammation and oxidative stress through PI3/AKT/GSK-3β pathway." (PMID 31736967, 2019).
Cognitive impairment (1 paper, 2024). Abnormal cognition is characterized by deficits in thinking, reasoning, or remembering. "Likewise, plasma concentrations of myostatin, PI3, TFF3, and PAPPA have been shown to identify at-risk individuals with high accuracy and well before clinical signs of cognitive impairment appear." (PMID 38337499, 2024).
diabetic foot ulcer (1 paper, 2025). "Fig7B and 7C displays the expression levels of CCL20, CXCL13, FGFR2, FGFR3, PI3, PLA2G2A, and S100A8 across the six cell types.The results showed that the key pathogenic genes of diabetic foot ulcer were mainly involved in keratinocytes and neutrophils." (PMID 40749079, 2025).
eczema (1 paper, 2023). "Notably, AMPs such as PI3 or LCE3A are also downregulated, while DCD, an antimicrobial component of sweat typically downregulated in eczema, shows the opposite direction." (PMID 37298605, 2023).
edema (1 paper, 2020). An abnormal accumulation of fluid beneath the skin, or in one or more cavities of the body. "This suggests that the PI3/Akt/mTOR signaling pathway may be involved in hypoxia induced lung edema." (PMID 32508639, 2020).
emphysema (1 paper, 2023). "Previous reports have linked the PI3/Akt pathway in reverting the CS‐induced emphysema, thus supporting our findings." (PMID 37078230, 2023).
endothelial dysfunction (1 paper, 2022). In vascular diseases, endothelial dysfunction is a systemic pathological state of the endothelium (the inner lining of blood vessels) and can be broadly defined as an imbalance between vasodilating and vasoconstricting substances produced by (or acting on) the endothelium. "Defibrotide can prevent the upregulation of endothelial dysfunction markers induced by a uremic environment, and downregulate the expression of HDACs through the PI3/AKT signaling pathway, thus playing a protective role in the endothelia." (PMID 36209090, 2022).
fibrosis (1 paper, 2023). the formation of excess fibrous connective tissue in an organ or tissue in a reparative or reactive process. "Therefore, the interaction between Tretinoin and PI3 might improve the lung inflammation and fibrosis." (PMID 37700323, 2023).
fungal infection (1 paper, 2025). "PI3 may be a potential clinical marker for early fungal infection monitoring, with significant implications for improving SFTSV outcomes." (PMID 39688402, 2025).
Hyperinsulinemia (1 paper, 2021). An increased concentration of insulin in the blood. "A significant protein upregulation compared to the untreated control was induced by metformin, but not by hyperinsulinemia, for immune regulatory factors such as IL5 and peptidase inhibitor 3 (PI3, elafin (ELAF))." (PMID 33690729, 2021).
Infertility (1 paper, 2022). "Studies in humans reported a negative feedback loop between NDRG4 activation and consequent PI3-Akt suppression, which could explain the role of NDRG4 in infertility via PI3-Akt suppression." (PMID 36005579, 2022).
ischemia (1 paper, 2021). A hypoperfusion of the BLOOD through an organ or tissue caused by a PATHOLOGIC CONSTRICTION or obstruction of its BLOOD VESSELS, or an absence of BLOOD CIRCULATION. "In ischemic stroke studies, BZA reduced the infarct volume by strongly inhibiting the ischemia-induced phosphorylation of ERK1/2 and modulating PI3/AKT in both female and male rats." (PMID 34681670, 2021).
keloid (1 paper, 2020). An irregularly shaped, elevated mark on the skin caused by deposits of excessive amounts of collagen during wound healing. "Our results associate keloid tissues with an inflammatory milieu representing multiple T-helper pathways, including the Th2 (e.g. IL-4R, CCL11, TSLP, TNFSF4/OX40L, TNFRSF4/OX40), Th1 (e.g. IFNγ, CXCL10/11), Th17/Th22 (e.g. PI3, CCL20, S100As) axes, as well as the JAK/STAT signaling molecule JAK3." (PMID 33329590, 2020).
keratitis (1 paper, 2017). A corneal disease that is characterized by inflammation of the cornea. "The broad-spectrum antimicrobial activity of PI3 and SLPI proteins have led to investigation into their potential as treatments for infectious diseases, and could therefore be explored as adjunct antimicrobials for keratitis." (PMID 28573109, 2017).
mastitis (1 paper, 2025). Inflammation of breast tissue during lactation or postpartum due to an obstructed duct or infection. "Additionally, other infectious diseases, including Neospora caninum, bovine herpesvirus type 1 (BoHV-1), mastitis, Leptospira spp., bovine leukemia virus, and parainfluenza virus type 3 (PI-3), have been identified as risk factors." (PMID 40559538, 2025). "Studies identified associations with coinfections, such as Neospora caninum, bovine herpesvirus type 1 (BoHV-1), mastitis, Leptospira spp., bovine leukemia virus (BLV), and parainfluenza virus 3 (PI-3), and with symptoms such as abortion, fever, reproductive problems, and mortality." (PMID 40559538, 2025).
migraine (1 paper, 2025). "Five genes were replicated both in the migraine dataset and in IBD-Character: TMEM176A, TMEM176B, PI3, HIST1H2BD, and HIST1H2AD." (PMID 41010012, 2025).
Nephropathy (1 paper, 2013). A nonspecific term referring to disease or damage of the kidneys. "The role of the EGFR pathway, involving Pi3-AKT-Rac1, in cisplatin-induced nephropathy, could not be substantiated in further detail." (PMID 23457647, 2013).
Obesity (1 paper, 2023). Accumulation of substantial excess body fat. "In underexpressed genes, obesity did not affect PI3, CHI3L1, and IL-8 and significantly reduced CPA3 expression." (PMID 37445432, 2023).
Parkinson disease (1 paper, 2025). A progressive degenerative disorder of the central nervous system characterized by loss of dopamine producing neurons in the substantia nigra and the presence of Lewy bodies in the substantia nigra and locus coeruleus. "In this study, we identified seven hub genes—PI3, TMSB15A, CLEC4M, CD4, SEMA6A, PLXND1, and AVP—that collectively drive Parkinson’s disease progression through synergistic mechanisms." (PMID 41329689, 2025).
Proteus syndrome (1 paper, 2021). Proteus syndrome (PS) is a very rare and complex hamartomatous overgrowth disorder characterized by progressive overgrowth of the skeleton, skin, adipose, and central nervous systems. "Similar selective mechanisms have been shown in patients with Proteus syndrome and related disorders, in which somatic mutations within the AKT gene, as well as other genes within the PI3-AKT pathway, confer a growth advantage." (PMID 34284807, 2021).
pulmonary fibrosis (1 paper, 2022). Chronic progressive interstitial lung disorder characterized by the replacement of the lung tissue by connective tissue, leading to progressive dyspnea, respiratory failure, or right heart failure. "Furthermore, we show that DZNep treatment alone or in context of SARS‐CoV or SARS‐CoV‐2 infections reduces abundance of pulmonary fibrosis markers (e.g., SERPINE1, MMP14, and COL4A1) and increases levels of factors with antifibrotic activity (e.g., HOPX, PI3/ELAFIN, and SLPI)." (PMID 35833542, 2022).
rhabdomyosarcoma (1 paper, 2022). A rare aggressive malignant mesenchymal neoplasm arising from skeletal muscle. "Our results have highlighted aberrant miRNA expression and over-expression of several members of PI3-AKT, MAPK and apoptosis signaling pathways in fusion-negative rhabdomyosarcoma, particularly in tumors with unfavorable prognosis." (PMID 35158790, 2022).
skin aging (1 paper, 2023). The gradual irreversible changes in structure of skin that occur as a result of the passage of time.. "Molecular docking analysis showed that 8 key compounds had a high docked ability with AR, BCHE, HPGD and PI3, which were identified as specific biomarker for the diagnosis of skin aging." (PMID 37310405, 2023). "Then, we confirmed the down-regulated expressions of ABCC4, PTGER3, BCEH, HPGD, and MOXD1 in normal group, while AR, CXCR2, HSD17B2, ODC1, PI3, PLAU and THBS2 were up-regulated in skin aging group." (PMID 37310405, 2023). "In addition, ROC curve verified that these hub-target had certain sensitivity and specificity for the diagnosis of skin aging (AUC greater than 0.5), AR, BCEH, CXCR2, HPGD and PI3 performed well especially." (PMID 37310405, 2023).
thyroid (1 paper, 2015). "Furthermore, the cellular pathways stimulated by mutated RAS, including the MAPK and PI3/AKT signaling pathways, have been linked to thyroid tumorigenesis." (PMID 26253102, 2015).
trichoblastoma (1 paper, 2024). A benign hair follicle neoplasm with trichoblastic differentiation.
ventilator-associated pneumonia (1 paper, 2025). Serious INFLAMMATION of the LUNG in patients who required the use of PULMONARY VENTILATOR. "In ventilator-associated pneumonia (VAP), distinct gene expression profiles have been identified, showing downregulation of genes like PIK3R3, ATP2A1, PI3, ADAM8, and HCN4." (PMID 39941194, 2025).